SIRT1 (sirtuin 1)
Diseases named in the same sentence as SIRT1 in open-access papers (continued):
Sharing a sentence is not in itself a finding about the gene and the disease.
Hepatic steatosis (continued). "The purpose of this study was to investigate the effect of hepatic steatosis on the expression of the sirtuin 1 (SIRT1), along with the target mRNA and protein expressions and activities related to lipid metabolism in liver tissue." (PMID 32230804, 2020). "Bloodstream SIRT1, leptin and adiponectin (ELISA), total and trunk fat mass (FM) %, abdominal visceral adipose tissue, liver steatosis and epicardial fat thickness (EFT) were assessed." (PMID 33202604, 2020). "SIRT1 has important roles in maintaining normal liver function and its activation has beneficial effects against fatty liver disease." (PMID 33202604, 2020). "Both C3a and Asp promote the expression of Gly-tRFs via mediating the expression of CYP2E1, which contributes to the development of liver steatosis by regulating Sirt1 expression." (PMID 31076642, 2019). "Taken together, our data suggest that SIRT1 is the major sirtuin family member to mediate NAMPT’s role in alleviating ethanol-induced liver steatosis and injury." (PMID 30794635, 2019). "The present study provides a novel molecular mechanism by which moderate exercise alleviates the progression of renal dysfunction and hepatic steatosis through SIRT1-mediated regulation of metabolism and inflammation in diabetic db/db mice." (PMID 30988688, 2019). "For more convincing evidence of the beneficial effect of TSF against hepatic steatosis via SIRT1 induction, further studies are needed to investigate the metabolic changes in liver-specific SIRT1 knockout mice treated with vehicle or TSF." (PMID 31105592, 2019). "The activation of SIRT1-protein induction-mediated autophagy is an important protective mechanism against hepatic steatosis in caloric restriction, which is the most effective intervention for NAFLD progression to date." (PMID 31105592, 2019). "In conclusion, TSF improved lipid accumulation and hepatic steatosis by inducing the AMPK/SIRT1 pathway-mediated autophagy." (PMID 31105592, 2019). "The evidence is now emerging to suggest that hepatic steatosis induced by chronic alcohol exposure is mainly mediated by SIRT1." (PMID 30634538, 2019). "Our study has found that UDCA can activate SIRT-1 and reduce hepatic steatosis by increasing fatty acid β-oxidation and reducing SREBP-1c expression." (PMID 30884843, 2019). "At present, this study provides ample evidence that TSF-induced hepatic steatosis remission is dependent on AMPK/SIRT1-mediated autophagy." (PMID 31105592, 2019). "When challenged with a high-fat diet, liver-specific SIRT1 knockout mice develop hepatic steatosis, hepatic inflammation, and ER stress." (PMID 31717842, 2019). "Erythropoietin (EPO) alleviates hepatic steatosis by activating autophagy via SIRT1-dependent deacetylation of LC3." (PMID 31291980, 2019). "Although some studies have reported that SIRT1 inhibition in the liver can contribute to hepatic steatosis, there is some evidence that SIRT1 inhibition in the liver or adipocytes can enhance insulin sensitivity in animals exposed to a high-fat diet." (PMID 31683679, 2019). "miR-34a inhibition increases phosphorylated AMPKα through mediating SIRT1 to suppress the development of fatty liver." (PMID 29681936, 2018). "Overexpression of SIRT-1 ameliorates high fat diet induced hepatic steatosis with enhanced energy expenditure and improved glucose tolerance, whereas hepatic deletion of SIRT-1 exhibit a significantly increased triglyceride accumulation in hepatocytes." (PMID 29563875, 2018). "Sirt1 transgenic mice show better glucose tolerance and insulin sensitivity and are almost entirely protected from hepatic steatosis with HFD treatment." (PMID 30574122, 2018). "We detected the expression of these genes after treatment with PCB, PCBG, MPG, and the reference compound, QCT, which was reported to exert a preventive effect against hepatic steatosis probably through SIRT1/AMPK and PPARα pathways." (PMID 30154382, 2018).
Hepatic steatosis (continued). "Here, we analyze the impact of ER stress and SIRT1 in lipid metabolism and in fatty liver pathology, and their consequences on liver regeneration." (PMID 31225483, 2018). "Sirt1 also protects against a high-fat diet or alcohol consumption-induced hepatic steatosis via various metabolic pathways." (PMID 30055626, 2018). "Liver-specific deletion of SIRT1, as well as protein downregulation, resulted in hepatic steatosis, inflammation, and OS." (PMID 29516009, 2018). "Liver specific deletion of SIRT-1 contributes to increased inflammation, endoplasmic reticulum stress and hepatic steatosis." (PMID 29563875, 2018). "GC supplementation in obese NAFLD patients reduced inflammatory biomarkers (IL-6, TNF-α, and hs-CRP), ALT, and the degree of fatty liver and increased Sirt1 compared with placebo." (PMID 30263038, 2018). "Due to important and beneficial roles of Sirt1 in different metabolic pathways involved in the metabolic disorders especially fatty liver, many studies have assessed the activation of Sirt1 for effectively preventing the progress of the fatty liver disease." (PMID 30263038, 2018). "Recent data suggest, that metformin alleviates hepatic steatosis through kinase-independent and SIRT1-mediated effects on the autophagy machinery." (PMID 30246793, 2018). "Silencing of miR-34a using a miR-34a inhibitor was shown to prevent liver injury and improve hepatic steatosis through its target proteins, like PPARα and SIRT1, which can activate AMP-activated protein kinase in an animal model of NAFLD." (PMID 28250026, 2017). "Mice administered 0.02% scopolin for 8 weeks exhibited improved phenotypes of HFD-induced hepatic steatosis along with increased hepatic SIRT1 activity and protein expression." (PMID 28533555, 2017). "Taken together, these results suggest that the changes of factors that lead to hepatic steatosis contribute to down-regulation of hepatic SIRT1 in L-G6pc-/- mice." (PMID 28558013, 2017). "The net outcome was a decrease in the expression of SIRT1 in the livers of L-G6pc-/- mice, providing a possible link between hepatic steatosis and defective autophagy in GSD-Ia." (PMID 28558013, 2017). "Study has been done regarding in the partial absence of Sirt1 activity, even normal diet also can increase liver steatosis in Sirt1+/- mice, and possible mechanism is related with the increase of lipid synthesis in the liver of Sirt1+/- mice." (PMID 28360860, 2017). "Scopolin attenuated hepatic steatosis through activation of SIRT1-mediated signaling cascades, a potent regulator of lipid homeostasis." (PMID 28533555, 2017). "Our results demonstrated that inhibition of NAMPT aggravated the HFD- or oleic acid-induced hepatic steatosis through suppressing Sirt1-mediated signaling pathway." (PMID 28449683, 2017). "Resveratrol is able to decrease hepatic steatosis and lipid metabolic disorder, and enhance the antioxidant ability by up-regulating SIRT1 expression in KKAy mice." (PMID 28903430, 2017). "In this study, we show that hepatic G6Pase-α deficiency alters the activity and/or expression of several lipid regulators, leading to hepatic steatosis and reduced expression of SIRT1, an enzyme that regulates the activity of many proteins via deacetylation." (PMID 28558013, 2017). "Liver-specific deletion of Sirt1 results in hepatic steatosis and inflammation in mice, while treatment with Sirt1 activators or Sirt1 overexpression ameliorates fatty liver and reduces lipogenic gene expression." (PMID 28042486, 2016). "In mice, it has been shown that the deletion of SIRT1 leads to hepatic steatosis with normal and high fat diet." (PMID 26890260, 2016). "In this study, we identified that the SIRT1-PPARγ-MGAT1 axis is critically involved in alcoholic hepatic steatosis, making MGAT1 a potential therapeutic target of hepatic fatty liver disease." (PMID 27404390, 2016).
Hepatic steatosis (continued). "We demonstrated that SIRT1 overexpression attenuates ethanol-induced hepatic steatosis, in which PPARγ acetylation is decreased." (PMID 27404390, 2016). "In this study, we established that SIRT1 is involved in alcoholic hepatic steatosis by regulating the acetylation of PPARγ and its activity." (PMID 27404390, 2016). "RSV can act as a positive regulator of sirtuin 1 (Sirt1) to improve the metabolic process of aging, hepatic steatosis and diabetes." (PMID 27098390, 2016). "This is in agreement with our data that showed liver-specific knockout of Mfn2 in mice is linked to impaired glucose metabolism, to decreases in SIRT1, SIRT3, and insulin signaling resulting in hepatic steatosis." (PMID 28097021, 2016). "Prolonged fasting induces lipid deposition in the livers of wild-type mice, but severe hepatic steatosis in liver-specific SIRT1 knockout mice." (PMID 27148532, 2016). "Taken together, these data indicate that SIRT1 has a protective and beneficial role in alcohol-induced hepatic steatosis." (PMID 27404390, 2016). "SIRT1 also supports fatty acid oxidation and oxidative phosphorylation in the liver, suppresses hepatic steatosis, and acts in white adipose to suppress lipid accumulation." (PMID 27058248, 2016). "Future studies into the area are warranted and would likely shed light on key mechanistic information regarding the importance of SIRT1 in alcohol-mediated fatty liver disease." (PMID 26473939, 2015). "In mouse models of obesity, a high-fat diet induces persistent activation of c-Jun N-terminal kinase 1 (JNK1), which enhances SIRT1 degradation in the liver, leading to hepatic steatosis." (PMID 25541949, 2014). "Benefits of Sirt1 overexpression consisted of better glucose tolerance, as well as protection against hepatic steatosis." (PMID 25140191, 2014). "The involvement of Sirt1/6 in the RGZ-mediated effect against hepatic steatosis was evaluated by single or double knockdown of Sirt1 and Sirt6 in a hepatocyte steatosis model." (PMID 25133775, 2014). "Hepatic deletion of SIRT1 impairs PPARα activity, decreases fatty acids oxidation, and results in hepatic steatosis and inflammation in response to high-fat feeding." (PMID 24759758, 2014). "Altogether, most approaches indicate that SIRT1 overexpression improves cholesterol metabolism and prevents hepatic steatosis, while SIRT1 deletion in the liver favors lipid accumulation." (PMID 24567900, 2014). "Res is able to attenuate hepatic steatosis and lipid metabolic disorder and enhance the antioxidant ability in KKAy mice, possibly by up-regulating Sirt1 expression and the phosphorylation of AMPK." (PMID 25140191, 2014). "When challenged with a high-fat diet, liver-specific Sirt1 knockout mice develop hepatic steatosis and inflammation." (PMID 25195642, 2014). "In an SIRT1 heterozygous knockout mice study, acceleration of hepatic steatosis and increased inflammatory gene expressions were observed in the liver." (PMID 24073959, 2013). "miR-34a was first identified as a post-transcriptional regulator of SIRT1 during the regulation of apoptosis and fatty liver disease." (PMID 24009212, 2013). "Resveratrol and SRT1720, both of which are Sirt1 activators, ameliorate fatty liver with reduced lipid synthesis and increased rates of fatty acid oxidation through Sirt1 and adenosine monophosphate-activated protein kinase (AMPK) activation." (PMID 22363635, 2012). "In contrast, over-expression of SIRT1 decreases hepatic steatosis and improves insulin sensitivity that leads to improved glucose homeostasis." (PMID 23203037, 2012).
Hepatic steatosis (continued). "Overexpression of Sirt1 and Sirt6 was recently reported to improve glucose control, hepatic steatosis and inflammation." (PMID 21373642, 2011). "We found that resveratrol with 4 g/kg dose partially prevented hepatic steatosis and hepatocyte ballooning and induced skeletal muscle SIRT1 and SIRT4 expression while other examined parameter were unaffected by resveratrol." (PMID 21977315, 2011). "When challenged with a high-fat diet, liver-specific Sirt1 knockout (KO) mice develop hepatic steatosis, hepatic inflammation, and endoplasmic reticulum stress." (PMID 21549004, 2011). "BAC-based transgenic mice overexpressing SIRT1 in various tissues exhibited normal fat mass and protected against high-fat diet-induced impaired glucose tolerance and hepatic steatosis due to decreased hepatic glucose production." (PMID 21738790, 2011). "In contrast, heterozygous SIRT1 knockout (SIRT1+/-) mice developed severe hepatic steatosis on high-fat diets, accompanied by lower energy expenditure and increased inflammation." (PMID 22185590, 2011). "Conversely, liver-specific Sirt1 knockout mice developed hepatic steatosis, hepatic inflammation, and endoplasmic reticulum stress." (PMID 21373642, 2011). "Loss of SIRT1 from hepatocytes impairs PPARα signaling, resulting in decreased fatty acid oxidation and leading to the development of hepatic steatosis on a high-fat diet, whereas overexpression of SIRT1 induces expression of PPARα gene targets." (PMID 20814433, 2010). "Menin deficiency in high-fat diet (HFD) models leads to hepatic steatosis, while menin overexpression reduces triglyceride accumulation, suggesting the menin-SIRT1 axis as a potential therapeutic target for hepatic steatosis and age-related metabolic disorders." (PMID 40052151, 2025). "In vitro and in vivo studies revealed that inhibiting miR-181b expression alleviated hepatic steatosis, while overexpressing SIRT1 blocked the pathological effects of miR-181b, suggesting that targeting miR-181b could be a therapeutic strategy for MASLD." (PMID 40668532, 2025). "The purpose of this study was to determine whether aerobic exercise may improve liver steatosis by adjusting the miR-34a-PPARα/SIRT1 signal pathway." (PMID 41223206, 2025). "The regulatory role of miR-34a-PPARα/SIRT1 in liver steatosis was summarized in." (PMID 41223206, 2025). "In a word, PPARα/SIRT1-AMPK pathway was involved in miR-34a-regulated hepatic steatosis." (PMID 41223206, 2025). "SIRT1 transgenic mice, which show reduced PPARγ acetylation, are protected from ethanol-induced hepatic steatosis, suggesting that modulating PPARγ acetylation through SIRT1 could be an effective therapeutic strategy." (PMID 40052151, 2025). "Interestingly, LOF of the NAD+-dependent deacetylase SIRT1 has been associated with impaired FFA oxidation and hepatic steatosis in fasted mice and during a high-fat diet." (PMID 41132685, 2025). "Other studies have shown that SIRT1 has a significant impact on liver lipid metabolism, oxidative stress, and inflammation by means of epigenetic modifications that help mitigate the progression of fatty liver disease." (PMID 40427561, 2025). "Furthermore, it inhibits ferroptosis through the SIRT1/Nrf2 pathway, improving fatty liver disease, and blocks NLRP3-Caspase-1-GSDMD-mediated pyroptosis in H9C2 and RAW264.7 cells." (PMID 40391374, 2025). "In addition, the selective SIRT1 activator SRT1720 attenuates high-fat diet (HFD)-induced liver steatosis." (PMID 38807218, 2024). "In this context, AMPK, Sirt1, SREBP1c, and PPARα signaling pathways have been highlighted as major molecular targets for novel therapeutic agents aimed at inhibiting the progression of hepatic steatosis." (PMID 39334796, 2024). "Furthermore, a selective inhibitor of the SIRT1 counteracted the positive effects of 1,25(OH)2D on hepatic steatosis and inflammation." (PMID 38543036, 2024).
Hepatic steatosis (continued). "In alcohol-associated hepatic steatosis, ROS-induced oxidative stress may suppress energy metabolism signaling pathways linked to AMPK and Sirt1, while promoting the production of TNF-α." (PMID 39334796, 2024). "Decreased SIRT1 activity impairs fatty acid oxidation and exacerbates hepatic steatosis." (PMID 39355507, 2024). "Here, we show that the presence of hepatic steatosis in a model of MASLD induced by fructose-drinking water was accompanied by a reduction in hepatic SIRT1 protein levels and an upregulation of VLDLR levels, suggesting a potential relationship between these two proteins." (PMID 38807218, 2024). "Moreover, liver-specific SIRT1 knockout mice fed a high-fat Western diet display impaired lipid metabolism and develop hepatic steatosis, inflammation, and endoplasmic reticulum stress." (PMID 38543036, 2024). "Thus, SIRT1 levels are reduced in obese patients and obese patients with severe hepatic steatosis compared with obese patients with mild hepatic steatosis." (PMID 38612504, 2024). "Likewise, mice with a liver-specific knockout of Sirt1 are prone to hepatic steatosis, while SIRT1 overexpression attenuates hepatic steatosis in mice fed an HFD." (PMID 38807218, 2024). "Additionally, SIRT1 exerts a favorable influence in the regulation of hepatic lipid metabolism, and the stimulation of SIRT1 activity impedes the advancement of fatty liver diseases." (PMID 39236049, 2024). "An in vitro study indicated that the protective effect of E2 treatment on hepatic steatosis could be abolished when ERα or SIRT1 was selectively inhibited." (PMID 38136219, 2023). "Moreover, hepatocyte-specific deletion of SIRT1 alters fatty acid metabolism and leads to hepatic steatosis and inflammation." (PMID 37190114, 2023). "In conclusion, the present investigation has provided initial evidence that Que-metformin, an innovative combined therapeutic approach, can reduce hepatic steatosis in PA-induced HepG2 cells by stimulating autophagy through the cAMP/AMPK/SIRT1 pathway and diminishing inflammatory cytokines." (PMID 38116565, 2023). "Considering the roles of AMPK phosphorylation, SIRT1, autophagy, cAMP, and inflammation in the emergence of hepatic steatosis, they might represent prospective potential targets for treating NAFLD." (PMID 38116565, 2023). "Then, we performed an in vitro study to explore the hypothesis that E2 treatment could protect mitochondrial function, reduce lipid oxidation, and prevent hepatic steatosis by upregulating the ERα/SIRT1/PGC-1α pathway." (PMID 38136219, 2023). "Specifically, Sirt1 was determined to play a beneficial role in protecting HFD‐induced or alcohol consumption‐induced hepatic steatosis, yet the mechanism underlying its metabolic functions is not fully understood." (PMID 36905134, 2023). "Further studies are still needed to clarify how TLR4 regulates SIRT1 in hepatocytes and whether Cim supplementation could alleviate high-fat diet-induced hepatic steatosis and liver injury." (PMID 35355867, 2022). "Indeed, sirtuin-1 overexpression has been shown to provide protection against high-fat-induced hepatic steatosis in mice via the upregulation of gene expression, enhancing fatty acid oxidation and the downregulation of lipogenic gene expression." (PMID 36139771, 2022). "Therefore, regulation of the SIRT1-SREBP-1c axis is one of the major mechanisms linking the pathogenesis of alcohol-induced hepatic steatosis." (PMID 36557739, 2022). "Regulation of FGF21/SIRT1 participates in the improvement of steatohepatitis and hepatic steatosis." (PMID 34984826, 2022). "Moreover, some LYC metabolites are bioactive, particularly apo-10′-lycopenoic acid (ALA), the major metabolite of LYC known to suppress hepatic steatosis and inflammation by stimulating sirtuin 1 (SIRT1)." (PMID 35743545, 2022). "In relation to this, accumulating studies demonstrate that SIRT1 may influence the progression of hepatic steatosis in an autophagy mediated manner." (PMID 35909524, 2022).